SMURF2 (SMAD specific E3 ubiquitin protein ligase 2)
Diseases named in the same sentence as SMURF2 in open-access papers (continued):
Sharing a sentence is not in itself a finding about the gene and the disease.
pancreatic cancer (9 papers, 2018 to 2025). "Co-expression analysis confirmed that SMURF1 and SMURF2 were highly correlated and co-regulated in pancreatic cancer." (PMID 40342823, 2025). "Analysis and comparison of OS, DSS and PFI revealed that SMURF1 and SMURF2 were expressed at higher levels in deceased pancreatic cancer patients compared to living patients." (PMID 40342823, 2025). "Meanwhile, high expression of SMURF2 indicated a positive correlation with the histological grade of pancreatic cancer (P<0.050)." (PMID 40342823, 2025). "This dataset was utilized in the study to analyze the expression of SMURF1 and SMURF2 and their correlation with pancreatic cancer staging and patient survival." (PMID 40342823, 2025). "The authors found that miR-15b was upregulated in pancreatic cancer and promoted the epithelial–mesenchymal transition by degrading SMURF2." (PMID 37628628, 2023). "The ChIP-qPCR analysis also revealed the binding of CBX3 and H3K9me3 to the promoter region of SMURF2 in pancreatic cancer cells." (PMID 35637952, 2022). "CBX3 was found to play a key role in cancer progression by suppressing the expression of SMURF2 in pancreatic cancer." (PMID 35637952, 2022). "Our findings revealed that cigarette smoking induced the overexpression of CBX3 in pancreatic cancer cells and tissues, which consequently suppressed the expression of SMURF2 and enhanced the malignant potential of pancreatic cancer." (PMID 35637952, 2022). "In pancreatic cancer cells, miR‐15b downregulate Smurf2 expression, attenuating the inhibition of TGF‐β to promote EMT." (PMID 34783198, 2021). "A recent study showed that the expression of SMURF2, a tumor suppressor gene, is inhibited by miR-15b in pancreatic cancer." (PMID 33317198, 2020). "Recent studies have also reported that the SMURF2 gene was inhibited by miR‐322/503 in the intestinal epithelial cell and by miR‐15b in pancreatic cancer." (PMID 31581360, 2019). "Studies conducted using pancreatic cancer cells also suggest that Smurf2 acts as a tumor suppressor." (PMID 30116722, 2018). "Interestingly, the levels of miR-15b-5p in pancreatic cancer have been investigated in relation to SMURF2, a protein with a tumor-suppressive function." (PMID 37628628, 2023). "SMURF2 has been shown to suppress the ability of tumor formation of pancreatic cancer cells." (PMID 35637952, 2022). "In pancreatic cancer, overexpression of Smurf2 inhibits TGF-β to mediate EMT." (PMID 35509688, 2022). "Furtherly, CBX3 could promote cell proliferation through the suppression of SMAD specific E3 ubiquitin protein ligase 2 (SMURF2) in pancreatic cancer." (PMID 35637952, 2022). "Moreover, we detected the expression of CBX3 and SMURF2 in tissue microarrays from pancreatic cancer biopsies (n = 91)." (PMID 35637952, 2022). "In summary, the YBX1/CBX3/SMURF2 signaling axis may be a promising therapeutic target in patients with smoking-related pancreatic cancer." (PMID 35637952, 2022). "Therefore, the YBX1/CBX3/SMURF2 signaling axis may be considered as a promising target for the treatment of smoking-related pancreatic cancer." (PMID 35637952, 2022). "Patients with pancreatic cancer were divided into high and low expression groups based on the median expression levels of SMURF1 and SMURF2." (PMID 40342823, 2025). "Collectively, these results demonstrate that YBX1 upregulates CBX3, which consequently represses SMURF2 and activates the TGF-β signaling pathway and promotes malignant progression in pancreatic cancer." (PMID 35637952, 2022). "CBX3 promoted malignant progression partly by inhibiting the expression of SMURF2 and activating the TGF-β pathway in pancreatic cancer." (PMID 35637952, 2022). "We also revealed that CBX3 enhanced pancreatic cancer progression, likely by inhibiting the expression of SMAD specific E3 ubiquitin protein ligase 2 (SMURF2) and promoting the activation of TGF‐β signaling." (PMID 35637952, 2022).
pancreatic cancer (continued). "Taken together, our results indicate that CBX3 suppresses SMURF2 expression and activates the TGF-β pathway in pancreatic cancer." (PMID 35637952, 2022). "To this end, we constructed pancreatic cancer cells with stable knockdown for CBX3, SMURF2, or both together." (PMID 35637952, 2022). "As CBX3 was found to repress SMURF2 expression, we then evaluated the relevance of SMURF2 in CBX3-induced pancreatic cancer progression." (PMID 35637952, 2022). "The results from the Cox regression analysis demonstrated that an elevated expression of SMURF2 had a negative correlation with the survival time of patients with pancreatic cancer, which is of great importance for predicting patient survival." (PMID 40342823, 2025). "CBX3 ablation simply upregulated the expression of SMURF2 but not SMURF1 in pancreatic cancer cells." (PMID 35637952, 2022). "Consistently, simultaneous silencing of CBX3 and SMURF2 in pancreatic cancer cells did not restore the ability of tumor growth in vivo." (PMID 35637952, 2022). "Additionally, their expression was found to correlate with the clinical stage of pancreatic cancer, so it is postulated that increased expression of SMURF1 and SMURF2 may have prognostic value in identifying patients with a poor outcome." (PMID 40342823, 2025). "MTS and colony formation assays demonstrated that SMURF2 knockdown enhanced proliferation of pancreatic cancer cells; however, co-knockdown of SMURF2 and CBX3 could not reverse this process." (PMID 35637952, 2022). "Furthermore, SMURF2 but not SMURF1 was downregulated in CBX3-overexpressed pancreatic cancer cells." (PMID 35637952, 2022). "In this study, we demonstrated that CBX3 downregulated SMURF2 but not SMURF1, consistent with the biological function of CBX3 in pancreatic cancer." (PMID 35637952, 2022).
prostate carcinoma (9 papers, 2010 to 2023). A carcinoma that arises from epithelial cells of the prostate gland. "In a study of prostate cancers, Smurf2 mRNA levels were lower in advanced tumors compared to less advanced organ-confined tumors, suggesting an association of Smurf2 downregulation with tumor progression." (PMID 36612252, 2022). "In a study on prostate cancers, Smurf2 mRNA levels were lower in advanced tumors compared to less advanced organ-confined tumors, suggesting association of Smurf2 downregulation with tumor progression." (PMID 24485087, 2014). "The reduced protein levels of KAP1 following SMURF2 depletion were also observed in other cancer cell models, including cervix carcinoma HeLa cells, prostate carcinoma DU-145 cells, and breast adenocarcinoma MDA-MB-468 cells." (PMID 35406379, 2022). "It is reported that the high expression of Smurf2 is closely related to bone metastasis of prostate cancer." (PMID 35509688, 2022). "Bortezomib has been shown to inhibit the proliferation of prostate cancer cells by reducing Smurf2 expression." (PMID 35710591, 2022). "The increased levels of A‐lamins after Smurf2 knockdown were also observed in other human cell models: in mammary epithelial MCF‐10A cells, breast adenocarcinoma MCF‐7 cells, and in prostate carcinoma DU‐145 cells." (PMID 29405587, 2018).
colon cancer (8 papers, 2014 to 2025). "Collectively, these data suggest that Smurf2 was associated with stem cell-like properties of colon cancer cells." (PMID 35361871, 2022). "In vitro experiments using colon cancer cell lines demonstrated that short interfering RNA knockdown of Smurf2 increased cell migration and tumor sphere formation." (PMID 35361871, 2022). "Additionally, reversible ubiquitination of SATB1 by USP47 and SMURF2 promotes colon cancer proliferation." (PMID 41208974, 2025). "Schisandrin lowered SIRT1 protein expression, and there was a negative association between SIRT1 and the stimulation of SMURF2, which inhibits colon cancer cell proliferation and dissemination." (PMID 39451522, 2024). "As Smurf2 is significantly correlated with the stem cell-like properties of colon cancer cells, Smurf2 may be a target in the progression of CRC from original tumor growth to metastatic cascade and even recurrence after the initial hepatectomy." (PMID 38339403, 2024). "Sch B also indirectly regulates Smad ubiquitination regulatory factor 2 (SMURF2) by suppressing the protein expression of Sirtuin 1 (SIRT1) and restrains the growth and metastasis of colon cancer cells." (PMID 39995410, 2025). "Moreover, Pu’s group found that SMURF2 protein expression was induced by schisandrin B and that SMURF2 expression is negatively correlated with SIRT1 expression, thus hindering cell growth and metastasis of colon cancer." (PMID 36831013, 2023).
pulmonary fibrosis (7 papers, 2019 to 2025). Chronic progressive interstitial lung disorder characterized by the replacement of the lung tissue by connective tissue, leading to progressive dyspnea, respiratory failure, or right heart failure. "miR411-3p and miR-27a-3p inhibit silica- and bleomycin-induced pulmonary fibrosis by suppressing Smurf2 expression." (PMID 34198949, 2021). "We initially examined repression of the E3 ubiquitin ligases SIAH1, SMURF1, and SMURF2, which have been identified as targets of miR-424 in several cancers as well as pulmonary fibrosis." (PMID 32117091, 2020). "miR-411-3p 203, 204 targets Smurf2 to inhibit the activation of the TGF-β/smad signaling pathway and thereby inhibit bleomycin-induced dermal fibrosis and silica-induced pulmonary fibrosis." (PMID 39113708, 2024). "Smurf2 is induced by TGF-β-signaling and promotes pulmonary fibrosis and obstructive kidney fibrosis." (PMID 34198949, 2021). "For instance, Smurf1 and Smurf2, which facilitate the ubiquitin-dependent degradation of the unmethylated Smad7-TβR complex, reduce TGF-βsignaling and may thus mitigate pulmonary fibrosis." (PMID 40901482, 2025). "Moreover, our results showed Smurf2 downregulation in lung tissues of IPF patients with relevance to clinical severity, as well as in a BLM-induced lung fibrosis animal model." (PMID 36611161, 2023).
breast tumor (6 papers, 2014 to 2024). "Despite the independent association between Smurf2 and CNKSR2 expression with progressive breast tumor stages, the expression pattern of Smurf2 and CNKSR2 showed a significant positive association (P < 0.001) between each other among non-malignant and malignant tumors." (PMID 29534682, 2018). "The expression and localization of SMURF2 were analyzed in 666 human normal and cancer tissues, with primary focus on prostate and breast tumors." (PMID 31003445, 2019). "Altogether, the expression of Smurf2 and CNKSR2 displayed a statistically significant association with progressive grades of breast tumor samples as evidenced by Chi squared test." (PMID 29534682, 2018). "Concomitantly, we observed that expression of Smurf2 and CNKSR2 was associated with stage of breast tumor progression, showing increased expression from normal, hyperplastic breast samples, and fibroadenoma to in situ carcinoma to invasive breast carcinoma." (PMID 29534682, 2018). "Eventhough our descriptive analysis indicated a statistically significant association between Smurf2 and CNKSR2 with progressive breast tumor cases, we further analyzed the association between expression status of Smurf2 relative to CNKSR2 in non-malignant and malignant tumors." (PMID 29534682, 2018). "Together, these results suggested that elevated Smurf2 levels in breast tumours and cancer cell lines might contribute to the transforming property of human breast cells." (PMID 25191523, 2014). "PIAS3 reduction in breast tumor promotes the PIAS3 and Smurf2 pathway in tumor progression and metastasis; PIAS3-Smurf2 SUMOylation mechanism still requires more investigation in breast tumor metastasis." (PMID 38590645, 2024). "However, CNKSR2 does not exhibit a significant upregulation at the mRNA level in breast tumor samples compared to normal breast tissues, which indicate that expression status of Smurf2 and CNKSR2 is mainly associated at the protein level rather than at the mRNA level." (PMID 29534682, 2018).
diabetic nephropathy (6 papers, 2014 to 2026). "There was however a decrease in FN and Smurf2 mRNA expression in the MH and ML groups compared with the diabetic nephropathy group (P < 0.05), and this decrease was more pronounced in the MH group compared with the ML group (P < 0.05)." (PMID 24511554, 2014). "The expression of FN mRNA and Smurf2 mRNA increased in each experimental group compared with the NC group, especially in the diabetic nephropathy group (P < 0.01)." (PMID 24511554, 2014). "In this study, we discovered that Smurf2, a member of the UPP family, increased in the diabetic nephropathy group, concomitantly with increased expression of TGF-β and FN, followed by decreased expression of Smad7." (PMID 24511554, 2014).
osteoarthritis (6 papers, 2016 to 2023). A noninflammatory degenerative joint disease occurring chiefly in older persons, characterized by degeneration of the articular cartilage, hypertrophy of bone at the margins and changes in the synovial membrane. "Accordingly, Smurf2‐deficient mice were less susceptible to the pathological development of osteoarthritis compared to wild‐type animals (Huang, Veien, Zhang, Ayers & Song, 2016)." (PMID 29405587, 2018). "Overexpression of Smad ubiquitin regulatory factor 2 (Smurf2) in chondrocytes was reported to cause spontaneous osteoarthritis (OA) in mice." (PMID 26815610, 2016). "Lead, an environmental toxin, impaired TGF-β signaling pathway via upregulation of Smurf2 and downregulation of pSmad2 and pSmad3, leading to osteoarthritis in articular chondrocytes." (PMID 37359559, 2023). "Circ_0116061 regulated the expression of miR-200b-3p and SMURF2, leading to modulation of cell apoptosis, proliferation, and inflammation in osteoarthritis chondrocytes." (PMID 37359559, 2023). "This phenotype could be due to upregulation of beta-catenin in the chondrocytes after Smurf overexpression, indicating that Smurf2 might be responsible for the development of osteoarthritis." (PMID 37359559, 2023). "Smurf2 has been observed to regulate osteoarthritis via targeting β-catenin in cartilage." (PMID 37359559, 2023). "Nicolai’s study found that the overexpression of SMURF2 reduced the levels of RUNX2 and TGFBR1 in an osteoarthritis system, and our investigation added direct information about the relationship between RUNX2 and TGFBR1." (PMID 36611957, 2022). "Smurf2 was strongly expressed in human osteoarthritis compared with nonarthritic cartilage." (PMID 37359559, 2023).
non-small cell lung carcinoma (5 papers, 2019 to 2025). A group of at least three distinct histological types of lung cancer, including non-small cell squamous cell carcinoma, adenocarcinoma, and large cell carcinoma. "However, the detailed effect of SMURF2 on non-small cell lung cancer has not been fully understood." (PMID 37497010, 2023). "In non-small cell lung cancer (NSCLC), curcumin stabilizes and activates the NLRP3 inflammasome by suppressing Smurf2, an E3 ubiquitin ligase that normally facilitates NLRP3 degradation." (PMID 40806716, 2025). "In non-small cell lung cancer cell lines, fucoidan stimulates the ubiquitin-dependent degradation in vitro of TGF-RI/II via Smurf2/Smad7." (PMID 30621045, 2019).
atherosclerosis (4 papers, 2020 to 2023). A disease characterized by the build-up of fatty material and calcium deposition in the arterial wall resulting in partial or complete occlusion of the arterial lumen. "WWP2 is involved in vascular endothelial injury 123-124, SMURF1 in atherosclerosis 135-137 and pulmonary hypertension 127-132, and SMURF2 in myxomatous mitral disease 158-160 and vascular endothelial injury 168-170." (PMID 33110392, 2020). "The molecular mechanism of SMURF2 in atherosclerosis provides an insight into targeted treatment of the disease." (PMID 33110392, 2020). "However, the roles of macrophage-derived EVs carrying miR-503-5p in atherosclerosis via Smad7-Smurf1/Smurf2-TGF-β axis have not been investigated yet." (PMID 33872218, 2021).
hepatocellular carcinoma (4 papers, 2003 to 2022). A malignant tumor that arises from hepatocytes. "SMURF2 expression is upregulated in several cancers like hepatocellular carcinomas (HCC) and colorectal cancer (CRC)." (PMID 33418880, 2021). "This relief of inhibition depends upon the wild-type PY motif in RNF11, as the RNF11 mtPY does not produce this effect when contransfected with the Smurf2 vector in TGFβ-treated HepG2 human hepatoma cells." (PMID 14562029, 2003). "Smurf2, one of C2-WW-HECT domain E3 ubiquitin ligases, is closely related to the development and progression in different cancer types, including hepatocellular carcinoma (HCC)." (PMID 35509688, 2022).
osteoporosis (4 papers, 2017 to 2023). A condition of reduced bone mass, with decreased cortical thickness and a decrease in the number and size of the trabeculae of cancellous bone (but normal chemical composition), resulting in increased fracture incidence. "Here the authors show that both germline and osteoblast-specific Smurf2-deficient mice have osteoporosis as a result of increased osteoblast RANKL production and excess osteoclastogenesis." (PMID 28216630, 2017). "For example, in a study on osteoporosis, it was found that miR-708-5p inhibited osteoclast differentiation by targeting SMURF2, while miR-708-3p promoted osteoclast differentiation by regulating the expression of CDR1as." (PMID 36279099, 2023).
Stroke (4 papers, 2020 to 2022). Sudden impairment of blood flow to a part of the brain due to occlusion or rupture of an artery to the brain. "Notably, Smurf2 has been reported to be intensively associated with the diagnosis of atrial fibrillation and stroke, which was identified from a protein-protein interaction (PPI) network previously constructed." (PMID 33815059, 2021). "In a similar finding, Smurf2 overexpression was noted to promote neuron differentiation after a stroke." (PMID 33722608, 2021). "For example, the molecular target of hsa-miR-676-3p, SMURF2, is involved in neurodifferentiation in recovery phase following ischemic stroke, while its other targets, PTPRB and ANP32B, have also been previously investigated in experimental stroke models." (PMID 35328807, 2022).
triple-negative breast carcinoma (4 papers, 2014 to 2024). An invasive breast carcinoma which is negative for expression of estrogen receptor (ER), progesterone receptor (PR), and human epidermal growth factor receptor 2 (HER2). "This study provides evidence of posttranscriptional downregulation of Smurf2 in triple-negative breast cancers, and demonstrates that the loss of RB function is involved in microRNA-mediated interference with Smurf2 translation." (PMID 24485087, 2014). "The new link from RB inactivation to Smurf2 downregulation is likely to play a role in malignant phenotypes of triple-negative breast cancer cells." (PMID 24485087, 2014). "SMURF2 was previously identified as downregulated in triple-negative breast cancer." (PMID 39208653, 2024). "Consistently, human triple-negative breast cancer cell lines such as BT549, MDA-MB-436, DU-4475 and MDA-MB-468 cells showed significantly lower expression of Smurf2 protein, compared to ER + or HER2+ cell lines." (PMID 24485087, 2014).